TNF (tumor necrosis factor)
Diseases named in the same sentence as TNF in open-access papers (continued):
Sharing a sentence is not in itself a finding about the gene and the disease.
intrauterine growth restriction (19 papers, 2012 to 2025). "Elevated levels of IFN‐γ and TNF‐α are associated with fetal growth restriction, microcephaly, and placentates." (PMID 41407556, 2025). "The treatment with TNF-α inhibitors has been associated with oligohydramnios and fetal growth restriction, though it is unclear whether these outcomes are attributed to the medication or the disease itself." (PMID 40703281, 2025). "The most common adverse pregnancy outcomes following the use of TNF-α inhibitors (e.g., etanercept) are intrauterine growth restriction, spontaneous abortion, and preterm birth." (PMID 38586585, 2024). "In IUGR and SGA pregnancies, maternal adiponectin concentration negatively correlates with maternal TNFα, suggesting a prevalent inflammatory condition in a mother whose pregnancy is complicated by fetal growth restriction." (PMID 25045669, 2014). "The loss of the control of the production of these cytokines, with increase of TNF-α, is related to the risk for developing obstetric complications, particularly recurrent fetal loss, GDM, hypertensive syndromes, and fetal growth restriction." (PMID 22462002, 2012). "Indeed, increased levels of pro-inflammatory cytokines such as interleukin-8, interferon-gamma, and tumor necrosis factor-alpha have been observed in individuals born with fetal growth restriction." (PMID 34576323, 2021). "Compared with the PM group, the PMS group significantly reduced the incidence rate of intrauterine growth restriction (IUGR) (p < 0.05) and significantly decreased the concentration of the proinflammatory cytokine (TNF-α) level in plasma (p < 0.05)." (PMID 37443982, 2023). "TNF-α decreases in the macrosomic offspring of mothers with GDM, and contrarily, it increases in the placentas of pregnancies that are complicated by fetal growth restriction." (PMID 22462002, 2012).
ischemia reperfusion injury (19 papers, 2009 to 2025). Adverse functional, metabolic, or structural changes in ischemic tissues resulting from the restoration of blood flow to the tissue (reperfusion), including swelling; hemorrhage; necrosis; and damage from free radicals. "Supplementation with Ori reduced the levels of SOD2, CAT, MDA, ROS levels, and IL-1β, TNF-α in hind limb muscle tissue of ischemia–reperfusion injury mice, suggesting that Ori plays a protective role against oxidative stress and the inflammatory response." (PMID 37375489, 2023). "High-mobility group box 1 has been nominated to be an early mediator of inflammation and organ damage in ischemia-reperfusion injury by increasing production of tumor necrosis factor-α, IL-1, IL-6, and other pro-inflammatory mediators." (PMID 35395776, 2022). "In vivo studies showed that pterostilbene improved cardiac function and decreased oxidative stress and inflammation markers (tumor necrosis factor α TNFα, interleukin 1β IL-1β, myeloperoxidase activity) in a rat model of ischemia-reperfusion injuries." (PMID 33546142, 2021). "In a pre-clinical model of ischemia-reperfusion injury, prazosin administration resulted in decreased expression of IL-6, TNF-α, IL-10, and IL-1, and prevented mortality." (PMID 33869251, 2021). "In an animal model of ischemia-reperfusion injury, pterostilbene improved cardiac function and reduced markers of oxidative stress and inflammation such as tumor necrosis factor-alpha (TNF-α), interleukin-1-beta (IL-1β) and myeloperoxidase activity." (PMID 29522491, 2018). "Several studies have shown that BQ123 has a beneficial influence on the TNF-α level in the lung tissue of rats treated with cigarette smoke extract, in rat hearts with ischemia-reperfusion injury, and in patients after bypass grafting." (PMID 26823945, 2016). "In the pathogenesis of intestinal ischemia-reperfusion injury, TNF-α and IL-1 play important roles in the progress of intestinal mucosa injury." (PMID 25210512, 2014). "Here, we sought to further examine the activation of necroptosis in kidney ischemia-reperfusion injury (IRI) and from TNFα-induced severe inflammatory response syndrome (SIRS), two models of RIPK3-dependent injury." (PMID 29500402, 2018). "The lung ischemia-reperfusion injury (IRI) model demonstrated both increased peak airway pressure, poor gas exchange and increased levels of TNFα." (PMID 23013526, 2012). "In a model of ischemia-reperfusion injury, migrating CD4 T cells were shown to interact with endothelial cells to promote platelet adhesion and Kupffer cells produced a similar effect via tumor necrosis factor (TNF)-α secretion." (PMID 36389830, 2022). "In a rat model of ischemia–reperfusion injury caused by elevated IOP, morphine inhibited the production of the proinflammatory cytokine tumor necrosis factor α (TNFα), an effect antagonized by naloxone, a nonselective antagonist of opioid receptors." (PMID 31374938, 2019). "In a rat model of ischemia/reperfusion injury, HBO treatment improved intestinal barrier function by raising the partial pressure of oxygen and oxygen supply in blood, maintaining ATP and aerobic metabolism, and inhibiting TNF-α expression, therefore preventing intestinal epithelium from apoptosis." (PMID 33178107, 2020).
left ventricular hypertrophy (19 papers, 2015 to 2025). Enlargement of the LEFT VENTRICLE of the heart. "Elevated levels of TNF-α and IL-1β have also been associated with reduced survival in chronic HD patients, and TNF-α has been associated with left ventricular hypertrophy in these patients." (PMID 40004669, 2025). "In CKD patients, elevated levels of IL-6 and TNF-α have been linked to left ventricular hypertrophy, arterial stiffness, and increased cardiovascular mortality." (PMID 41011058, 2025). "Data showed that TNF infusion causes myocardial damage, myocyte shrinkage, and left ventricular hypertrophy in rats." (PMID 35052719, 2021). "However, our results suggested that a higher plasma TNF concentration was associated with a higher risk of left ventricular hypertrophy and could be a potential risk factor for impaired diastolic function in patients with early-onset CAD." (PMID 38396488, 2024). "It has been reported that inhibition of TNF-α levels can reduce systolic blood pressure and relieve left ventricular hypertrophy and activate the Akt/eNOS pathway to improve vascular endothelial function." (PMID 35360657, 2022). "In accordance with the previous study, the results showed that TNF-α strongly correlated with fibrosis, suggesting that inflammation process triggered fibrosis formation and is macroscopically represented by left ventricular hypertrophy." (PMID 26941790, 2016). "Recent study from our laboratory found that TNF-α inhibition reduced systolic BP and left ventricular hypertrophy and activated AKT/eNOS pathway, improving vascular function in hypertensive rats." (PMID 26504819, 2015). "We recently found that TNF-α inhibition with infliximab reduced systolic BP, left ventricular hypertrophy, and vascular inflammation in spontaneously hypertensive rats (SHR)." (PMID 26504819, 2015). "Adiposity is associated with low-grade inflammation and elevated levels of inflammatory markers such as tumor necrosis factor-alpha which reduces adiponectin and thereby increases left ventricular hypertrophy through AMP kinase signaling and alpha-adrenergic receptor stimulation." (PMID 29417316, 2018). "TNF-α knockout mice may inhibit BP elevation and left ventricular hypertrophy." (PMID 31196042, 2019). "Furthermore, some studies have found that TNF-α inhibition reduces SBP and left ventricular hypertrophy via AKT/eNOS pathway activation, thereby improving vascular function in hypertensive rats." (PMID 29752343, 2018).
mesothelioma (19 papers, 2011 to 2025). A usually malignant and aggressive neoplasm of the mesothelium which is often associated with exposure to asbestos. "The IKK Kinase Assay corroborated these findings, demonstrating increased IKKalpha/beta activity in mesothelioma cell lines compared to normal mesothelial cells, both in the absence and presence of TNF-alpha." (PMID 40016284, 2025). "Employing the NF-κB-Luciferase reporter system, we assessed NF-κB activity in response to TNF-α treatment in both normal mesothelial cells and mesothelioma cell lines." (PMID 40016284, 2025). "Here, we demonstrated that treatment of mesothelioma tumors with si-m/h-VDAC1-B decreased both TNF-α and the activated p-NF-kB." (PMID 35883451, 2022). "The ability of normal mesothelial and mesothelioma cells to survive/proliferate in presence of TNF-α is intriguing." (PMID 21880146, 2011). "Next, we employed an ELISA EMSA test to assess the DNA-binding activity of each NF-κB subunits, in the different cell lines, revealing a notable activity of DNA binding of p65 and RelB, which was intensified upon TNF-α treatment in mesothelioma cell lines IST-Mes2 and MPP89." (PMID 40016284, 2025). "Interestingly, the presence of TNF-alpha exacerbated this increase, indicating a heightened responsiveness in mesothelioma cells." (PMID 40016284, 2025). "Like naftopidil in mesothelioma cells, HUHS1015 also increased expression of factors implicated in the extrinsic apoptosis pathway, such as the cytokine TNF-α in MKN45 gastric cells; however, this effect has been called into question due to the very high concentrations of HUHS1015 used." (PMID 32727149, 2020). "Insensitivity to the combination of SM and TNFα has also been reported for mesothelioma cells." (PMID 27551497, 2016). "Mesothelioma cell lines exhibited an augmented nuclear translocation of p65 and increased phosphorylation of cytosolic IKK, which were exacerbated upon TNF-alpha treatment." (PMID 40016284, 2025). "Although proinflammatory mediators like tumor necrosis factor alpha (TNF-α) and interleukin (IL)-1β can induce uPAR expression in mesothelial and mesothelioma cells through transcriptional regulation, we found that these mediators also reduce LRP1 expression." (PMID 34707211, 2021). "B-cell-activating factor of the tumor necrosis factor (TNF) family (BAFF; also known as B lymphocyte stimulator), a CD40L-related molecule produced by myeloid cells, was also identified in 3D mesothelioma spheroids." (PMID 22737246, 2012). "The heightened NF-κB activity, observed even in the absence of TNF-α treatment, suggests intrinsic dysregulation within mesothelioma cells." (PMID 40016284, 2025). "Moreover, it was shown to induce apoptosis of mesothelioma cells NCI-H28, NCI-H2052, NCI-2452 and MSTO-211H by activating caspase 3 and 8 and increasing TNF-α mRNA expression and Fas-Ligand secretion in NCI-H2052 however, this effect is only observed for high concentrations." (PMID 32727149, 2020). "Moreover, they reveal that unlike macrophages and monocytes, and like MSTO-211H human mesothelioma cells, human mesothelial cells do not require exogenous TNFα or lipopolysaccharide to initiate NLRP3-mediated cytokine release." (PMID 23937860, 2013). "In fact, HMGB1 stimulates the secretion of TNF-α from macrophages and activates protumoral factors such as NF-κB, leading to chronic inflammation, autophagy and mesothelial cell transformation; thus, targeting HMGB1 may be an additional potential therapy for mesothelioma." (PMID 36232554, 2022). "A dampened effector response (IFNα2, IFNγ, MIP1α, TNFα and TNFβ) was detected in NSCLC PE, but not mesothelioma or benign PE." (PMID 31741710, 2019). "Mesothelioma-derived factors did not affect the ability of mature DCs to stimulate alloantigen-specific T cell proliferation, but did reduce mature DC production of pro-inflammatory cytokines, IL-12 and TNF-α, which may have downstream effects on the type of T cell response generated." (PMID 25886502, 2015).
mesothelioma (continued). "While preclinical models support the ability of TNF-α to also enhance ICI therapy, there are no active clinical trials involving NGR-hTNF and ICI therapy in NSCLC due to the manufacturer of NGR-hTNF discontinuing the product after a Phase III mesothelioma trial did not meet its primary endpoint." (PMID 34868953, 2021).
myopia (19 papers, 2017 to 2026). "Chronic inflammation, characterized by elevated cytokines like IL-6 and TNF-α, has been implicated in scleral remodeling and thinning, processes central to myopia development." (PMID 40571595, 2025). "Studies show that inflammatory factors like tumor necrosis factor-alpha (TNF-α), interleukin-6 (IL-6), and nuclear factor kappa B (NF-κB) are significantly elevated in myopia models, suggesting a key role for the immune response in myopia development." (PMID 41191163, 2025). "In FDM models, CSA treatment mitigated refractive changes; downregulated c-Fos, IL-6, TNF-α, and NF-κB; and enhanced IL-10 expression, supporting its potential in inflammation-targeted myopia therapy, although further clinical validation is needed." (PMID 41191163, 2025). "Upregulated expression of c-Fos, nuclear factor κB (NF-κB), interleukin (IL)-6, and tumor necrosis factor (TNF)-α were demonstrated from an experimental myopia model." (PMID 41224847, 2025). "These inflammatory factors are significantly elevated in both animal models and clinical samples of myopia, and they activate inflammatory mediators, such as TNF-α and IL-6, primarily through the NF-κB signaling pathway." (PMID 41191163, 2025). "In contrast, TNF-α triggers paracrine feedback loops in the retina or sclera, which play important roles in myopia progression." (PMID 39006849, 2024). "Meanwhile, CSA can decrease c-Fos, IL-6, TNF-α, and NF-κB expression and increase IL-10 immunoreactivity, suggesting that anti-inflammatory agents can effectively slow myopia progression." (PMID 39006849, 2024). "Elevated levels of TNF-α and IL-6 have been observed in tree shrews with myopia and patients with high myopia." (PMID 39239046, 2024). "By suppressing the levels of TNF-α, IL-1β, and IL-6 in human retinal pigment epithelium cells, resveratrol inhibits inflammatory effects to ameliorate myopia development." (PMID 37446088, 2023). "In myopia animal model, expressions of IL-6, IL-8, and TNF-α increase when compared with control eyes." (PMID 36242032, 2022). "Recent clinical and experimental studies provided evidence showing that atropine induced the downregulation of c-Fos, NF-κB, interleukin (IL)-6, and tumor necrosis factor (TNF)-α expression in hamsters with monocular form deprivation (MFD)-induced myopia." (PMID 34287272, 2021). "Reports show that high levels of IL-6 and TNF-α inflammatory cytokines initiate ocular inflammation and promote myopia progression in hamsters." (PMID 34285659, 2021). "Furthermore, recent experimental studies have reported that atropine reduces inflammatory markers such as c-Fos, NF-κB, IL-6, and TNF-α in form-deprivation myopia models, while promoting COL-1 expression." (PMID 41191163, 2025). "Our finding intimates that CRP and TNF-α might serve as protective elements against myopia’s evolution." (PMID 39239046, 2024). "TNF-α may also trigger paracrine feedback loops in the retina or sclera, leading to myopia progression and the activation of NF-κB11." (PMID 39006849, 2024). "Noteworthy findings include significant associations of IL-2 [IVW odds ratio (OR): 1.003, 95% CI: 1.001–1.005, P=0.001], IL-2ra (IVW OR: 1.002, 95% CI: 1.000–1.003, P=0.049), CRP (IVW OR: 0.996, 95% CI: 0.994–0.999, P=0.002), and TNF-α (IVW OR: 0.995, 95% CI: 0.994–0.996, P<0.001) with myopia risk." (PMID 39239046, 2024). "Although our results indicate a negative correlation between TNF-α and the incidence of myopia, it is crucial to note the limited number of SNPs associated with TNF-α in our analysis." (PMID 39239046, 2024). "We postulate that the expression of inflammatory markers, including NF-κB, TGF-β, IL-1β, IL-6, IL-8, and TNF-α, may contribute to the chronic inflammatory state observed in myopia." (PMID 39006849, 2024). "In our study, we found that IL-6, IL-8, and TNF-α expressions were higher in the myopia eye." (PMID 36242032, 2022).
myopia (continued). "Furthermore, RPE cells contribute to myopia progression by secreting inflammatory cytokines such as TNF-α and IL-6, which are upregulated in allergic conjunctivitis and have been shown to disrupt epithelial barriers and promote ocular tissue remodeling leading to axial elongation." (PMID 41191163, 2025). "Furthermore, TNF-α may exacerbate myopia progression and NF-κB activation by triggering paracrine feedback loops in the retina or sclera." (PMID 41191163, 2025). "Similar results have been validated in animal studies, where the induction of myopia leads to increased TGF-β and matrix metalloproteinase-2 (MMP-2) expression, accompanied by significant increases in IL-6, IL8, TNF-α and MCP-1." (PMID 41191163, 2025). "T1DM can decrease accommodation of the lens and ciliary muscles, leading to myopia, and T2DM, an inflammatory disease that leads to elevated IL-1β, IL-6, TGF-β, and TNF-α levels, can also exaggerate myopia progression." (PMID 39006849, 2024). "Animal models of experimental myopia showed that FJE, PVE, and FJE plus PVE treatments inhibited axial elongation, as well as NF-κB, TGF-β, IL-1β, IL-6, IL-8, and TNF-α inflammatory factors and collagen expression." (PMID 39006849, 2024). "Studies have shown that prolonged inflammation can exacerbate myopia by enhancing the expression of inflammatory components such as MMP-2, TGF-β, IL-1β, IL-6, and TNF-α." (PMID 39006849, 2024). "This analysis indicated that INFG, TNF, IL1B, EGF, HGF and OSM would be predicted to stimulate recovery from induced myopia (activators)." (PMID 38390290, 2023). "While the progression of myopia was enhanced through the treatment of lipopolysaccharide (LPS) or peptidoglycan (PGN), the expression level of IL-6, TNF-α, c-FOS, and nuclear factor κB increased." (PMID 28828383, 2017). "In addition, previous research showed that myopia progression was slowed down by cyclosporine A (CSA) and CSA treatment further reduced the expression of IL-6, TNF-α, c-FOS, and NF-κB in the eye." (PMID 34285659, 2021). "In order to study the effect of resveratrol on the PI3K–AKT, MAPK, and NFκB pathways, involved in myopia progression, ARPE-19 cells were incubated with TNF-α, IL-6, and IL-1β, alone and with combinations of these cytokines, for 10 min prior to the 10 min treatment with resveratrol." (PMID 34287272, 2021). "Thus, a vicious cycle develops between continuously induced TNF-α, IL-6, and IL-1β inflammatory responses in the RPE cells that would affect the levels of IL-6, IL-8, and MCP-1 intraocularly, which would promote myopia progression." (PMID 34285659, 2021).